SOD1 (superoxide dismutase 1)
Diseases named in the same sentence as SOD1 in open-access papers (continued):
Sharing a sentence is not in itself a finding about the gene and the disease.
steatosis (32 papers, 2011 to 2026). Increased lipid within the cytoplasm of cells. "FFA-induced steatosis in HepG2 cells is associated with ROS production and consequent lipid peroxidation, which is also strictly related to the decrease in some antioxidant enzymes such as SOD1 and a concomitant increase in proinflammatory mediators including TNF-α." (PMID 36985448, 2023). "Specifically, the gene of superoxide dismutase 1/2 (SOD1/2) was highly expressed in the steatosis groups (P < 0.05); this gene can convert superoxide (O2−) to hydrogen peroxide (H2O2) and oxygen (O2)." (PMID 38837944, 2024). "This was unexpected as SOD1 is involved in the prevention of TAG accumulation during high-fat diet induced steatosis in mice." (PMID 26846427, 2016). "Oleic acid could also induce steatosis in HepG2 cells in a dose-dependent manner, decrease the expression of PPAR-α and superoxide dismutase-1, increase lipid peroxide production and lead to cell proliferation inhibition." (PMID 35770013, 2022). "In addition, there was increased Nrf2 expression accompanied by low SOD1 expression in the liver, suggesting that HFFD may induce hepatic insulin resistance and subsequent steatosis through the enhancement of increased free fatty acid influx into the portal system and hepatic oxidative stress." (PMID 26265929, 2015).
Down syndrome (30 papers, 2008 to 2026). "Because a trisomy of the 21st chromosome is the cause for Down’s syndrome and SOD1 is mapped to the region where the putative causative gene is thought to be present, an elevation in SOD1 activity has been the suspected cause of Down syndrome." (PMID 35326151, 2022). "The cognitive impairments and premature signs of aging associated with Down syndrome have been associated with the SOD1/GPx ratio in the brain." (PMID 33805942, 2021). "Superoxide dismutase Sod1 and stefin B are both encoded on chromosome 21 in humans and are overexpressed in brains of patients with Down syndrome." (PMID 31766320, 2019). "In fact, in 1984, the first paper about Down's Syndrome was published, and in 1993, the first SOD1 gene mutations associated with ALS were described." (PMID 21603028, 2011). "For instance, Down syndrome (DS), caused by a genetic imbalance of chromosome 21 which contains genes coding for enzymes implicated in oxidative stress (e.g., Cu/Zn superoxide dismutase, SOD1), is characterized by a breach in antioxidant defenses." (PMID 32707949, 2020). "In Down syndrome, increased interleukin-6 and SOD1; in Fragile X syndrome, elevated FMR1 mRNA and cytokine changes; and in Rett syndrome, increased ammonium and metabolic profile disturbances are observed." (PMID 41465426, 2025). "Similar results were obtained in cultured primary nasal epithelial cells from Down syndrome children that exhibited an increased in SOD1 content (about 28%), compared to children with a normal karyogram, as well as in the plasma of Down syndrome children." (PMID 33805942, 2021). "Several reports have demonstrated the overexpression and/or overactivation of SOD1 not only in the amniotic fluid of Down syndrome fetuses, but also in several cells and tissues of Down syndrome patients." (PMID 33805942, 2021). "The role of SOD merits a different type of discussion when considering ALS, in which a mutant overactive SOD1 has been identified, and Down syndrome, in which chromosome 21 trisomy has been associated with the overexpression of SOD1 in patients." (PMID 33805942, 2021). "Expression levels of Down syndrome-related genes such as SOD1, DYRK1A, ETS2, APP, and DSCR1 in chromosome 21 are comparable with the gene number, i.e., three 21 chromosomes." (PMID 30760866, 2019). "The SOD1 activity of a person with Down syndrome (trisomy 21) is 50% higher than in the normal population." (PMID 28956814, 2017). "SOD1 overexpression has also been investigated as a contributor to the pathology of Down syndrome, a condition in which SOD1 overexpression is well documented." (PMID 26823951, 2016). "A major reason for this is that SOD1 is located on human chromosome 21 in a region traditionally referred to as the “Down Syndrome Critical Region,” although nowadays this particular term is less accepted." (PMID 25983373, 2015). "Therefore, the overexpression of genes located on chromosome 21 (including SOD1) is considered to be an essential feature for the Down syndrome phenotype." (PMID 33805942, 2021). "Although the mechanism of how SOD1 promotes the Down syndrome phenotype is unknown, one possible explanation is the out proportion of SOD1 activity over glutathione peroxidase 1 activity, which leads to the overproduction of H2O2—a key senescence mediator." (PMID 28956814, 2017). "However, another investigation found the elevations of these lipid peroxidation markers in the blood of live individuals with Down syndrome to not be associated with either SOD1 or glutathione peroxidase." (PMID 40356974, 2025). "It should also be noted that superoxide dismutase 1 (SOD1) is located on chromosome 21, for which three copies exist in trisomy 21 (Down syndrome—DS) model mice." (PMID 40725125, 2025). "Nevertheless, both mouse models carry most of the gene complement of the Down syndrome critical region, including RCAN1, APP, SOD1 and DYRK1A." (PMID 30034324, 2018).
psoriasis (30 papers, 2016 to 2025). An autoimmune condition characterized by red, well-delineated plaques with silvery scales that are usually on the extensor surfaces and scalp. "Research also found that the activity of SOD1 was notably elevated in the plasma of individuals with psoriasis." (PMID 39456475, 2024). "No notable disparities were detected in the manifestation of SOD1 or SOD2 genes among patients and controls, as well as across various clinical subtypes of psoriasis." (PMID 39456475, 2024).
colon carcinoma (29 papers, 2014 to 2025). "The implantation of intestinal stents inhibited the expression of SOD1 in the colon tumors of the CC mice." (PMID 38535948, 2024). "Conversely, the implantation of intestinal stents statistically significantly inhibited SOD1 expression in the colon tumors of the CC mice (C-Blank: p < 0.01)." (PMID 38535948, 2024). "Our data showed that droxinostat induced oxidative stress and ROS production in colon cancer cells, which is supported by the decreased expression of catalase, SOD1 and SOD2 with droxinostat treatment." (PMID 30065760, 2018). "We then probed the status of SOD1 acetylation at K71 in a panel of colon cancer cells, and found that the basal level of SOD1 acetylation varied largely across the cells." (PMID 26008972, 2015). "Additionally, 120 μM diallyl disulfide has been reported to increase SOD1 mRNA expression in human colon cancer HT-29 cells, which, according to the authors, results in cell cycle arrest and apoptosis." (PMID 39796240, 2025). "Ac-SOD1 level was examined after 12 hr exposure to CPT treatment in the colon cancer cell lines." (PMID 26008972, 2015). "Acetylation was detected on flag-tagged SOD1 enriched from HCT116 colon cancer cells." (PMID 26008972, 2015). "The injection of Cd-O2/N2 atomized gas further significantly suppressed the expression of SOD1 (C-Blank and C-Control: p < 0.001; C-S-Blank: p < 0.05), SOD2 (C-Control: p < 0.05), and CAT (C-Blank and C-Control: p < 0.01) in the colon tumors of the CC mice." (PMID 38535948, 2024). "SOD3 is associated with inhibition of tumour growth and metastasis, while SOD1 and SOD2 are elevated in different stages of several cancers, including colon cancer, and can trigger proliferative and apoptotic signals depending on the amount of H2O2 produced." (PMID 36235125, 2022). "LLEFE was able to significantly (P < 0.05) upregulate SOD1, CAT, and GSH and significantly (P < 0.05) downregulate PI3K, Akt, and mTOR expression in HT-29 colon cancer cells." (PMID 35586809, 2022). "Overexpression of SOD varieties, namely, SOD1 and SOD2, was shown to render detoxification to oxaliplatin-resistant colon cancer cells." (PMID 33187272, 2020). "The implantation of intestinal stents inhibited the expression of Superoxide Dismutase 1 (SOD1) in the colon tumors of the CC mice, with no evident effects on the expression levels of NOX1, SOD2, and Catalase (CAT) enzymes." (PMID 38535948, 2024). "SOD1, although not predicted as a direct target of miR-143 or miR-145 in bioinformatics analysis (miRanda MiRBase, Target Scan and MiRDB), was reduced after miR-143 and miR-145 overexpression in human colon cancer cells, thus suggesting indirect targeting." (PMID 29360852, 2018).
melanoma (29 papers, 2015 to 2026). A malignant, usually aggressive tumor composed of atypical, neoplastic melanocytes. "Combined DGAT1 and SOD1 suppression caused fatal ROS overload and melanoma cell death, as well as suppressed tumor growth." (PMID 36776554, 2023). "In the present study, it was found that the addition of the studied flavones caused oxidative stress in the melanoma cells, for which there was also an increase of the SOD1, SOD2, GPX1 and CAT gene expression." (PMID 35059971, 2022). "In vitro, it reduced C32 melanoma cells’ viability, affecting the mRNA expression of the antioxidant enzymes superoxide dismutase-1 and glutathione peroxidase-1." (PMID 40364408, 2025). "From our data analysis, 14% of the melanoma patients showed alteration on the SOD1 gene, 7% on SOD2, and 4% on SOD3." (PMID 35326089, 2022). "Gene expression analysis of melanomas and other cancers indicated an upregulation of SOD2 expression, while a histological examination of pigmented melanoma tissue samples revealed the upregulated expression of both SOD1 and SOD2 compared to healthy skin." (PMID 35326683, 2022). "Though few studies are addressing the role of SOD1 and SOD3 in melanoma, it was shown that SOD1 is involved in melanogenesis and/or differentiation." (PMID 35326089, 2022). "Thus, combinatorial DGAT1 and SOD1 inhibition synergized to create a toxic overload of ROS in tumors, severely retarding the growth of melanoma cells in vivo." (PMID 35732120, 2022). "We asked whether low expression of the direct NRF2 targets G6PD and SOD1 would influence melanoma adhesion and invasion." (PMID 34951143, 2022). "Combinatorial DGAT1 and SOD1 inhibition led to a profound impairment of melanoma growth in vivo." (PMID 35732120, 2022). "Consequently, DGAT1 inhibition results in oxidative stress in melanoma cells but this is countered by adaptive up-regulation of ROS-neutralizing enzymes such as superoxide dismutase 1 (SOD1)." (PMID 35732120, 2022). "Moreover, a study on B16F10 murine melanoma cells has demonstrated that SOD1 (1–1000 ng/mL) inhibits melanin production within 24 h in a dose-dependent manner." (PMID 33805942, 2021). "Furthermore, DSF has been shown to inhibit superoxide dismutase 1 (SOD1) in melanoma cells by complexing Cu2+ in a way that SOD1 lacks Cu2+ for its activity." (PMID 33260923, 2020). "In melanoma cells, DGAT1 inhibition caused excess FA oxidation and ROS generation, accompanied by activation of nuclear factor erythroid 2-related factor 2 (NRF2) signaling, which reduces ROS-mediated cellular damage through upregulation of superoxide dismutase 1 (SOD1)." (PMID 36776554, 2023). "SOD1 is involved in melanogenesis and/or differentiation, while SOD3 overexpression inhibits the growth of specific melanoma cells." (PMID 37297001, 2023). "Upregulation of additional genes from the bile acid and peroxisome signaling pathways was also evident in TIL gene and pathway expression analysis, including upregulation of SOD1, ACSL5, FADS2, CAT, DHCR24, SLC27A2, and IDH2 in melanoma TILs compared to pCD8s." (PMID 38023136, 2023). "The complex of DSF and Cu (II)has been reported to inhibit the enzyme superoxide dismutase 1 (SOD1), one of the major enzymesthat mitigates oxidative damage in melanoma cells." (PMID 37376016, 2023). "According to our analysis, 66% of the isoforms presented differential expression on melanoma progression: NOS2, SOD1, NOX4, PRX3, PXDN and GPX1 are increased during melanoma progression, while CAT, GPX3, TXNIP, and PRX2 are decreased." (PMID 35326089, 2022). "Besides, iNOS, SOD1, NOX4, PRX3, PXDN and GPX1 are generally increased during melanoma progression, while CAT, GPX3, TXNIP and PRX2 are decreased." (PMID 35326089, 2022). "Accordingly, the topical administration of 1000 ng/mL SOD1 to HRM-2 melanin-possessing hairless mice before UVB 190 mJ/cm2 exposure decreased UVB-induced melanogenesis by blocking the aggravation of melanogenesis and thus potentially preventing melanoma development." (PMID 33805942, 2021).
melanoma (continued). "Assuming that ROS-neutralizing factors such as SOD enzymes were limiting the tumor inhibitory effects of DGAT1 antagonism, we next examined whether blocking the induction of SOD1 would augment the impact of DGAT1 inhibition on melanoma cell growth and survival." (PMID 35732120, 2022).
Arthritis (28 papers, 2012 to 2025). Inflammation of a joint. "This analysis presented a significant enrichment of arthritis-specific microglia with spinal microglia in the SOD1 model of ALS and thalamic microglia in the TNFtg mouse model of RA." (PMID 37349313, 2023). "We demonstrated that the mRNA expression of antioxidant enzymes sod1 and cat from whole blood had a significant linear correlation of more than 50% with pain scores, in a human cohort of arthritis." (PMID 28572711, 2017).
cerebral infarction (28 papers, 2011 to 2026). An ischemic condition of the brain, producing a persistent focal neurological deficit in the area of distribution of the cerebral arteries. "Brain infarction was significantly reduced in SOD1 transgenic mice after focal cerebral ischemia, while this effect disappeared in SOD1 transgenic mice after a permanent focal cerebral ischemia." (PMID 24949080, 2014). "In the MCAO model, Neutrophil therapy delivered SOD1/CAT and Se to the site of brain injury in mice and significantly alleviated the area of cerebral infarction in mice after IS." (PMID 38846099, 2024).
dementia (28 papers, 2012 to 2025). Loss of intellectual abilities interfering with an individual's social and occupational functions. "The reports of ALS in cases with MAPT and PGRN mutations have to be confirmed as does dementia in ALS resulting from SOD1 mutations." (PMID 24915640, 2014). "Dementia is unusual in mitochondrial disorders, but mitochondrial dysfunction has also been suggested to be important in a number of central degenerative disorders such as SOD1-associated ALS." (PMID 23498975, 2013). "Not only the APP gene is responsible for dementia in DS, GATD3A, SOD1, ERG, BACE2, DSCR1/RCAN1, APOE (19q13.32), BACE1 (11q23.3), IL1B (2q14.1), GSAP (7q11.23), UBB (17p11.2), and IRS1 (2q36.3) genes may also play a major role in dementia in DS." (PMID 35676933, 2022).
cataract (27 papers, 2009 to 2025). Partial or complete opacity of the crystalline lens of one or both eyes that decreases visual acuity and eventually results in blindness. "Accordingly, a study of 415 cataract patients has demonstrated an increased risk of cataracts in patients that are polymorphic for SOD1 due to a reduced capacity to scavenge superoxide radicals in lenses." (PMID 33805942, 2021). "When compared to healthy controls, the allele frequency of the G allele of SOD1–251A/G was significantly different in the cataract group (p=0.001, OR=1.479, 95% CI=1.208–1.810)." (PMID 21921984, 2011). "To date, no studies have been conducted to determine whether histone acetylation regulates SOD1 expression in senile cataracts and whether the regulation is associated with the development of cataracts." (PMID 27703255, 2016). "It is possible that histone acetylation regulates not only SOD1 expression in senile cataracts, but also SOD1 activity changes due to age and cataract formation." (PMID 27703255, 2016). "In the present study, the results showed that SOD1 protein level was much lower in all three types of cataracts than in clear normal lenses, which is consistent with the findings of previous studies." (PMID 27703255, 2016). "A study of polymorphisms of SOD-1, CAT, and GPx genes in cataract patients found that G/G genotype of the SOD-1 (251A/G polymorphism) was associated with an increased risk of cataract." (PMID 24876913, 2014). "SOD1 G/G genotype frequency was significantly higher in cataract patients (p=0.012, OR=1.642, 95% CI=1.129–2.389)." (PMID 21921984, 2011). "However, a similar study demonstrated the efficacy of SOD1 in the treatment of cataracts, as the overexpression of SOD1 in the whole lens prevents H2O2-induced oxidative damage to the lens." (PMID 30140407, 2018). "The development of cataracts after AA intervention might be due to decreased SOD1 expression and, consequently, increased oxidative insults caused by altered histone acetylation." (PMID 27703255, 2016). "Moreover, mice deficient in Sod1 have increased superoxide radicals in their lenses, decreased levels of the antioxidant glutathione, and develop cataracts earlier and with higher frequency, while overexpression of SOD1 in the lens prevented H2O2‐induced cataracts." (PMID 26912740, 2016). "Based on these results, it can be presumed that histone acetylation at −600 bp of SOD1 promoter might be the key to the regulation of SOD1 expression and histone deacetylation at −600 bp might contribute to the downregulation of SOD1 expression and the formation of cataracts." (PMID 27703255, 2016). "The activity of well-known antioxidant enzymes was also evaluated in the aqueous humor of POAG subjects, showing increased levels of GPx (2.9-fold), SOD (1.8-fold), and malondialdehyde (MDA, 8-fold) when compared with patients with cataracts." (PMID 34439995, 2021). "For cataracts, GPX1 and SOD1 were expressed highly in most tissues." (PMID 37052519, 2023). "It is suggested that SOD plays an important role in cataract prevention in diabetic conditions; in an experiment conducted on SOD1-null mice, it was shown that the SOD1-lacking animals developed cataracts faster after streptozotocin injection than wild-type mice." (PMID 32560082, 2020). "Moreover, we found compensatory overexpression of antioxidant enzymes (SOD1, GPx‐1, and catalase) in aged lenses with cataracts in VEGF‐Ahyper mice, but not in young lenses without cataracts." (PMID 26912740, 2016).
gastric cancer (25 papers, 2006 to 2025). A primary or metastatic malignant neoplasm involving the stomach. "In the present study, we investigated possible associations between polymorphisms of CAT C-262T (rs1001179) and SOD1 A251G (rs2070424) with susceptibility to gastric cancer." (PMID 27843986, 2014). "However, we found that the G allele of the SOD1 A251G polymorphism has protective effects against the risk of gastric cancer." (PMID 27843986, 2014). "The expression of SOD2 (Mn-SOD), superoxide anion scavenger, is elevated, but the expression of SOD1 (copper/zincSOD) is decreased while comparing gastric cancer tissues with their matching normal mucosa." (PMID 37143652, 2023). "In this study, we investigated the association between gastric cancer and the polymorphisms of CAT C-262T and SOD1 A251G." (PMID 27843986, 2014).